ST8SIA2 (ST8 alpha-N-acetyl-neuraminide alpha-2,8-sialyltransferase 2)
Description:
Catalyzes the transfer of a sialic acid from a CMP-linked sialic acid donor onto a terminal alpha-2,3-, alpha-2,6-, or alpha-2,8-linked sialic acid of an N-linked glycan acceptor through alpha-2,8-linkages (Probable). Therefore, participates in polysialic acid synthesis on various sialylated N-acetyllactosaminyl oligosaccharides (alpha-2,3-, alpha-2,6-, or alpha-2,8-linked sialic acid), including NCAM1, NCAM1 N-glycans, FETUB N-glycans, and to a lesser extent sialylparagloboside (SPG) and AHSG, which does not require the initial addition of an alpha 2,8-sialic acid (Probable). However, does not exhibit sialic acid-polymerase activity (By similarity). Catalyzes polysialic acid synthesis in the hippocampal on NCAM1 and supports neurite outgrowth. ST8SIA2-mediated polysialylation influences on oligodendrocyte differentiation and may promote the integrity of myelin and axons (By similarity).
Synonyms: SIAT8-B; ST8SiaII; STX; SIAT8B; ST8SIA-II; HsT19690
Tractability: Antibody: UniProt places it where antibodies can reach, with high confidence; its Gene Ontology location is reachable by antibodies, with high confidence; UniProt predicts a signal peptide or a membrane-spanning region. PROTAC: ubiquitination databases record sites on it.
Gene: Protein-coding gene on chromosome 15 (92,393,881 to 92,468,728, forward strand). Ensembl gene ENSG00000140557.
Subcellular location: Golgi apparatus membrane; Secreted; Cell membrane
Subcellular location (Human Protein Atlas): Golgi apparatus; Cytosol; Nucleoplasm; Predicted to be secreted
Pathways (Reactome):
Metabolism of proteins: N-Glycan antennae elongation; Sialic acid metabolism
Developmental Biology: NCAM1 interactions
Gene Ontology:
Molecular function: alpha-N-acetylneuraminate alpha-2,8-sialyltransferase activity; sialic acid binding; sialyltransferase activity
Biological process: ganglioside biosynthetic process; glycoprotein biosynthetic process; N-glycan processing; oligosaccharide metabolic process; sialylation; carbohydrate metabolic process; nervous system development; protein modification process; neuron differentiation; neuron projection extension; positive regulation of neuron apoptotic process; positive regulation of synapse assembly; response to cocaine
Cellular component: extracellular region; Golgi apparatus; Golgi membrane; plasma membrane; early endosome; perinuclear region of cytoplasm; recycling endosome
Genetic constraint (gnomAD): Loss-of-function variants: 22 observed, 36.61 expected, observed/expected ratio (o/e) 0.6, 90% interval 0.43 to 0.86. The upper end of that interval is the gene's LOEUF score, 0.86, which puts it in group 3 of 6, group 1 being the genes least tolerant of losing a copy. Missense variants: 380 observed, 494.2 expected, observed/expected ratio (o/e) 0.77, 90% interval 0.71 to 0.84. Synonymous variants: 204 observed, 203.75 expected, observed/expected ratio (o/e) 1, 90% interval 0.89 to 1.12.
Homologues: Orthologues: chimpanzee ST8SIA2 (99% identical), pig ST8SIA2 (98% identical), dog ST8SIA2 (98% identical), mouse St8sia2 (98% identical), guinea pig ST8SIA2 (98% identical), rat St8sia2 (98% identical), macaque ST8SIA2 (93% identical), rabbit ST8SIA2 (83% identical), tropical clawed frog st8sia2 (79% identical), zebrafish st8sia2 (62% identical). Paralogues in human: ST8SIA4 (57% identical), ST8SIA3 (35% identical), ST8SIA1 (27% identical), ST8SIA5 (26% identical), ST8SIA6 (25% identical).
Diseases named in the same sentence as ST8SIA2 in open-access papers:
ST8SIA2 is named in the same sentence as 31 diseases in open-access papers, as found by Europe PMC text mining. Sharing a sentence is not in itself a finding about the gene and the disease. The quoted sentences say what the papers report.
schizophrenia (26 papers, 2012 to 2024). A major psychotic disorder characterized by abnormalities in the perception or expression of reality. "Genome-wide association studies (GWASs) identified variants of ST8SIA2 or the loss-of-function mutations associated with psychiatric conditions such as schizophrenia, bipolar disorder, and autism." (PMID 39596031, 2024). "Genetic variants of the ST8SIA2 gene or loss-of-function mutations affecting ST8SIA2 have been shown to be associated with schizophrenia, bipolar disorder, and autism." (PMID 38529039, 2024). "Mice with ST8SIA2 deficiency exhibited schizophrenia-like behavioral abnormalities, including cognitive dysfunction, deficits in prepulse inhibition, and increased sensitivity to amphetamine-induced locomotion." (PMID 38529039, 2024). "Genetic variation in ST8SIA2 has been associated with schizophrenia, autism, and bipolar disorder, and St8sia2−/− mice show a number of related neurodevelopmental and behavioral phenotypes." (PMID 35115485, 2022). "Previously, a mutation at an open reading frame (ORF) of ST8SIA2 in a schizophrenia patient was analyzed biochemically." (PMID 35563598, 2022). "By genetic studies, variations in ST8SIA2 have been associated with schizophrenia, autism, bipolar disorder and depression." (PMID 35617589, 2022). "Fam174b is implicated in autism spectrum disorder and variants of the St8sia2 gene increase susceptibility to bipolar disorder, schizophrenia, and autism." (PMID 36712851, 2022). "ST8SIA2 is a neurodevelopmental gene that has been repeatedly associated with schizophrenia, but also with autism, bipolar disorder, and depression." (PMID 35115485, 2022). "Three SNPs (rs3759916, rs3759915, and rs3759914) in the promoter region of the ST8SIA2 gene are associated with schizophrenia risk and involved in its promoter activity." (PMID 34914745, 2021). "Abnormalities in polySia expression in the hippocampal dentate gyrus of St8sia2-deficient mice was also shown and these mice exhibited schizophrenia-like phenotypes." (PMID 33202622, 2020). "Genome-wide association studies have identified variations in the St8sia2 gene in association with several psychiatric disorders, including schizophrenia, autism, and bipolar disorder, all of which involve social abnormalities and aggression." (PMID 30089788, 2020). "Genetic association studies have identified that genes coding for NCAM and ST8SIA2 represent susceptibility loci for schizophrenia, autism and bipolar disorder, with a case study reporting violent behavior associated with ST8SIA2 deletion." (PMID 30089788, 2020). "In humans, certain single nucleotide polymorphisms (SNPs) of ST8SIA2 have been reported in patients with schizophrenia, and the promoter regions of (SNP-1 and SNP-3) were determined to be involved in schizophrenia in the Japanese populations." (PMID 33202622, 2020). "Among the six ST8 α-N-acetyl-neuraminide α-2,8-sialyltransferases (ST8SIA) existing in adult brains, ST8SIA2 is a schizophrenia-associated gene." (PMID 31455764, 2019). "It is suggested that the expression level of the ST8SIA2 gene is a genetic determinant of schizophrenia risk, and we found that a geographically differentiated non-risk SNP type (CGC-type) has significantly reduced promoter activity." (PMID 30044798, 2018). "Three SNPs (SNP1 at rs3759916, SNP2 at rs3759915, and SNP3 at rs3759914) in the upstream region of the ST8SIA2 gene are associated with schizophrenia risk and involved in promoter activity." (PMID 30044798, 2018). "Together with previous work, the current study shows enticing data supporting the implication of ST8SIA2 genetic variants in schizophrenia, and, notably, informs a potential mechanism for the protection against major mental illness in healthy individuals." (PMID 29353880, 2018).
schizophrenia (continued). "Here we focused on one particular schizophrenia-associated gene that encodes a sialyltransferase (ST8SIA2) and is expressed preferentially in the brain with the level being largely determined by three SNPs in the promoter region." (PMID 30044798, 2018). "In humans, chromosome 15q26 where ST8SIA2/STX is localized was reported as a common susceptibility region for both schizophrenia and bipolar disorder in a genome scan of Eastern Quebec families." (PMID 28538701, 2017). "Impairments of the polySia-expression and several single nucleotide polymorphisms (SNPs) of the polysialyltransferase (polyST) ST8SIA2 gene are reported to be associated with schizophrenia and bipolar disorder." (PMID 28538701, 2017). "ST8SIA2 is located on chromosome 15q25-26 and has been considered a positional and functional candidate gene for schizophrenia and BD, and significant associations have been reported in several different populations." (PMID 26418860, 2015). "Other groups have shown association with schizophrenia in Japanese and Chinese cohorts in the promoter region of ST8SIA2, which was selected as a candidate gene after NCAM1 was implicated in disease risk." (PMID 24651862, 2014). "We subsequently found evidence of disease association with variants in ST8SIA2 in both bipolar disorder and schizophrenia." (PMID 24651862, 2014). "Variants within ST8SIA2 have previously shown association with bipolar disorder, schizophrenia and autism." (PMID 24651862, 2014). "There is growing evidence of the involvement of ST8SIA2 in risk of mental illness, with the association of variants within the gene with bipolar disorder, schizophrenia and autism." (PMID 24651862, 2014). "Recently, a relationship between SNPs in the promoter region of the ST8SIA2 gene and schizophrenia was identified by genome-wide association studies in the Japanese and Chinese Han populations." (PMID 23675315, 2013). "This implies uniqueness of the ST8SIA2 gene in the schizophrenia-associated genes." (PMID 34914745, 2021). "The gene for a biosynthetic enzyme of polySia, ST8SIA2, actually contains mutations or significant SNPs that are statistically associated with mental disorders, e.g., SNP-7, rs3759916, and rs3759914 from schizophrenia patients in a Japanese population and rs2168351 from bipolar disorder patients." (PMID 32824359, 2020). "Since the quantity of PSA-NCAM has been suggested as a factor involved in schizophrenia, it is expected that the promoter activity of ST8SIA2 gene is a genetic determinant of schizophrenia risk through controlling the amount of enzyme that regulates PSA quantity." (PMID 30044798, 2018). "Furthermore, ST8SIA2 gene deficiency in mice results in decreased social motivation and increased aggressive behavior (i.e., schizophrenia-like phenotypes)." (PMID 30044798, 2018). "Based on these findings and previous studies of other populations indicating that ST8SIA2 is a candidate gene for both schizophrenia and BD, the current study investigated the genetic association between ST8SIA2 and schizophrenia and BD in the Korean population." (PMID 26418860, 2015). "Considering both functional aspects and recent genetic study results including those of the present study, ST8SIA2 may be a susceptibility gene for both schizophrenia and BD beyond the boundary of diagnosis." (PMID 26418860, 2015). "We identified a possible role of ST8SIA2 in the common susceptibility of schizophrenia and BD-I." (PMID 26418860, 2015). "Further, loss-of-function mutations have previously been reported in ST8SIA2 in schizophrenia." (PMID 24651862, 2014). "In addition, chromosome 15q26, which is the genomic region containing the gene encoding ST8SIA2, is related to schizophrenia and bipolar disorders among the population of Eastern Quebec." (PMID 23675315, 2013).
schizophrenia (continued). "Variants in the promoter of ST8SIA2 have previously shown association with schizophrenia in Japanese and Chinese cohorts, after the gene was selected as a functional candidate due to its interaction with NCAM, which has also previously shown association with bipolar disorder." (PMID 22693595, 2012). "As the structural and functional analyses of polySia have been established, the precise evaluations of these mutations and single nucleotide polymorphism (SNP)s of ST8SIA2 that have been reported to have some relationship with schizophrenia and bipolar disorder could be performed." (PMID 32824359, 2020). "Taken together, these findings indicate that ST8SIA2, a facilitator of neural plasticity which is highly expressed early in human brain development, may play a role in the genetic susceptibility for both bipolar disorder and schizophrenia." (PMID 22693595, 2012). "As autism is thought to be part of a broader spectrum of neurodevelopmental disorders, and shares genetic and clinical overlaps with both schizophrenia and bipolar disorder, it is possible that ST8SIA2 may be a generalised susceptibility gene for all three illnesses." (PMID 22693595, 2012). "The ST8SIA2 gene was identified as a schizophrenia-related gene because it is functionally involved in sensitivity to psychosocial stress, an environmental risk factor of schizophrenia." (PMID 34914745, 2021). "Lowered promoter activity of the ST8SIA2 gene is considered to be protective against schizophrenia by conferring tolerance to psychosocial stress." (PMID 34914745, 2021). "For example, the SNP-7 (rs545681995) of ST8SIA2 observed in a schizophrenia patient resulted in a lower enzymatic activity, which led them to produce lower quality and quantity of polySia–NCAM than those of wild type." (PMID 32824359, 2020). "Recently, the polySia and polySia biosynthesizing enzyme ST8SIA2 have been demonstrated to exhibit a relationship with mental disorders, such as schizophrenia, bipolar disorder, depression, and autism." (PMID 33202622, 2020). "Taken together with the finding that the promoter activity of ST8SIA2 is involved in schizophrenia, it appears that transcriptional change of ST8SIA2 has an impact on mental activities." (PMID 30044798, 2018). "Operation of positive selection on the CGC-type raises the possibility that ST8SIA2 is a promising target in understanding schizophrenia development." (PMID 30044798, 2018). "We also demonstrated that polySia-NCAM biosynthesized by a mutated polysialyltransferase (ST8SIA2/STX), which was found in patients with schizophrenia, was impaired not only in the structure but also in the reservoir scaffold function." (PMID 28538701, 2017). "In particular, the polySia biosynthesizing enzyme, ST8SIA2 (STX, siat8b), has been reported to have some association with schizophrenia, bipolar disorder, and small cell lung cancer." (PMID 28538701, 2017). "Genetic variants of SIGLEC3/CD33, SIGLEC11, and SIGLEC14 have been associated with neurodegenerative diseases such as Alzheimer’s disease, while sialyltransferase ST8SIA2 and SIGLEC4/MAG have been linked to psychiatric diseases such as schizophrenia, bipolar disorders, and autism spectrum disorders." (PMID 38529039, 2024). "Interestingly, St8sia2-KO mice are used as a model to evaluate schizophrenia phenotypes, such as prepulse inhibition (PPI), which were found to be the same as those found in schizophrenia patients." (PMID 35563598, 2022). "Interestingly, St8sia2–/– mice have reduced polysialylation and display schizophrenic-like behaviors including cognitive and behavioral deficits and it was proposed that genetic variation in ST8SIA2 in humans may have the potential to confer a neurodevelopmental predisposition to schizophrenia." (PMID 36504680, 2022). "ST8SIA2 is an important molecule regulating expression of the phenotype involved in schizophrenia." (PMID 34914745, 2021).
schizophrenia (continued). "Interestingly, the ST8SIA2 gene is involved in not only schizophrenia but also bipolar disorder and autism." (PMID 30044798, 2018). "The ST8 alpha-N-acetyl-neuraminide alpha-2,8-sialyltransferase 2 (ST8SIA2) gene, which encodes the alpha-2,8-sialyltransferase 8B enzyme that aids neuronal migration and synaptic plasticity, was previously implicated as a schizophrenia susceptibility gene." (PMID 29353880, 2018). "Considering gene function, ST8SIA2 could be related to the putative pathological mechanism of both schizophrenia and BD." (PMID 26418860, 2015). "Targeted gene studies for ST8SIA2 have been performed in patients with schizophrenia." (PMID 26418860, 2015). "Since growing evidence suggests that a neurodevelopmental deficit is important in the pathophysiological mechanism of schizophrenia and BD, ST8SIA2 could be a plausible functional candidate gene." (PMID 26418860, 2015). "In addition, several characteristic properties, such as brain structure, neural plasticity, and various morphological, cognitive, and emotional deficits related to schizophrenia have been observed in ST8SIA2- or ST8SIA4-SKO mice." (PMID 23675315, 2013). "Interestingly, several association studies have identified ST8SIA2 (also known as SIAT8B) as a risk gene for several neurodevelopmental and psychiatric disorders, including autism spectrum disorder (ASD), bipolar disorder and schizophrenia." (PMID 34650588, 2021). "Taken together, these results suggest that changes in the quantity and quality, particularly DP, of polySia, which are closely related with the enzymatic activity of ST8SIA2, lead to an altered binding affinities toward BDNF, FGF2, and DA, may be one of the underlying causes of schizophrenia." (PMID 23675315, 2013). "Interestingly, ST8SIA2 and NCAM are candidate genes for schizophrenia, a disorder in which interneuronal circuits are altered." (PMID 30787870, 2019). "To gain insight into an evolutionary basis of schizophrenia prevalence, we focus on the CGC-type (a non-risk type) of the ST8SIA2 gene because of its functional involvement in the illness." (PMID 30044798, 2018). "As NCAM is not the only substrate for ST8SIA2 and the underlying biosynthetic mechanisms of polySia by ST8SIA2 and ST8SIA4 are not well understood, it is important to focus on the contribution of glycoepitopes, such as polySia, to schizophrenia." (PMID 23675315, 2013).
bipolar disorder (16 papers, 2011 to 2024). A disorder of the brain that causes unusual shifts in mood, energy, activity levels and the ability to carry out day-to-day tasks. "Two intronic SNPs that are associated with bipolar disorder and autism, respectively, affect the expression of pre-mRNA and mRNA, and alter the cellular levels of ST8SIA2 and PSA." (PMID 30044798, 2018). "More recently, genome-wide association studies have implicated SNPs downstream of ST8SIA2 in risk of bipolar disorder, and variants in intron 2 have also been associated with autism spectrum disorder (verbal subtype)." (PMID 24651862, 2014). "Moreover, a GWAS of bipolar disorder in Han Chinese found strong association (P<6×10−6) with two SNPs which lie 30 kb downstream of ST8SIA2 in the C15orf32 gene." (PMID 22693595, 2012). "Single nucleotide polymorphisms (SNPs) of sialyltransferase ST8SIA2/STX, involved in production of PSA, are linked with psychiatric disorders, such as schizophrenia, bipolar disorder, and autism spectrum disorders." (PMID 30518374, 2018). "Although the GWAS result was not obtained in the same population as our cohort, this finding suggests that the combination of multiple DNA variants across multiple enhancers is an important mode of regulation at the ST8SIA2 locus in bipolar disorder." (PMID 24651862, 2014). "Recently, the chromosome where ST8SIA2, the human STX-encoding gene, is localized, 15q26, was reported as a common susceptibility region for both schizophrenia and bipolar disorder in a genome scan of Eastern Quebec families." (PMID 21826279, 2011). "We have exploited this technique to sequence the coding, intronic and flanking sequence of ST8SIA2 and its region of interaction in NCAM1, in lymphocyte DNA from individuals with bipolar disorder." (PMID 24651862, 2014). "To explore the role of sequence variation affecting PSA-NCAM formation, we conducted a targeted re-sequencing study of a ∼100 kb region – including the entire ST8SIA2 gene and its region of interaction with NCAM1 – in 48 Caucasian cases with bipolar disorder using the Roche 454 platform." (PMID 24651862, 2014).